MYOCD (myocardin)
Description:
Smooth muscle cells (SM) and cardiac muscle cells-specific transcriptional factor which uses the canonical single or multiple CArG boxes DNA sequence. Acts as a cofactor of serum response factor (SRF) with the potential to modulate SRF-target genes. Plays a crucial role in cardiogenesis, urinary bladder development, and differentiation of the smooth muscle cell lineage (myogenesis) (By similarity). Positively regulates the transcription of genes involved in vascular smooth muscle contraction (By similarity).
Synonyms: MYCD; MGBL
Tractability: PROTAC: UniProt records ubiquitination sites on it.
Gene: Protein-coding gene on chromosome 17 (12,665,890 to 12,768,949, forward strand). Ensembl gene ENSG00000141052.
Subcellular location: Nucleus
Subcellular location (Human Protein Atlas): Nucleoplasm
Pathways (Reactome):
Developmental Biology: Cardiogenesis
Gene Ontology:
Molecular function: DNA-binding transcription factor binding; protein binding; transcription coactivator activity; RNA polymerase II-specific DNA-binding transcription factor binding; histone acetyltransferase binding; histone deacetylase binding; R-SMAD binding
Biological process: cardiac muscle cell myoblast differentiation; negative regulation of amyloid-beta clearance; negative regulation of cell population proliferation; negative regulation of skeletal muscle cell differentiation; positive regulation of cardiac muscle cell differentiation; positive regulation of DNA-templated transcription; positive regulation of smooth muscle cell differentiation; positive regulation of smooth muscle contraction; positive regulation of transcription by RNA polymerase II; response to hypoxia; smooth muscle cell differentiation; urinary bladder development; cardiac muscle cell differentiation; cardiac vascular smooth muscle cell differentiation; cardiocyte differentiation; regulation of smooth muscle cell differentiation; transcription initiation-coupled chromatin remodeling; heart development; negative regulation of platelet-derived growth factor receptor-beta signaling pathway; negative regulation of vascular associated smooth muscle cell migration; negative regulation of vascular associated smooth muscle cell proliferation; positive regulation of gene expression; positive regulation of miRNA transcription; positive regulation of transforming growth factor beta receptor signaling pathway; regulation of muscle cell differentiation; and 2 more
Cellular component: nucleus; chromatin
Genetic constraint (gnomAD): Loss-of-function variants: 24 observed, 85.41 expected, observed/expected ratio (o/e) 0.28, 90% interval 0.2 to 0.4. The upper end of that interval is the gene's LOEUF score, 0.4, which puts it in group 1 of 6, group 1 being the genes least tolerant of losing a copy. Missense variants: 1,079 observed, 1,189.7 expected, observed/expected ratio (o/e) 0.91, 90% interval 0.86 to 0.95. Synonymous variants: 446 observed, 469.12 expected, observed/expected ratio (o/e) 0.95, 90% interval 0.88 to 1.03.
Homologues: Orthologues: chimpanzee MYOCD (99% identical), macaque MYOCD (98% identical), rabbit MYOCD (90% identical), guinea pig MYOCD (86% identical), dog MYOCD (86% identical), pig MYOCD (85% identical), rat Myocd (82% identical), mouse Myocd (79% identical), tropical clawed frog myocd (59% identical), Caenorhabditis elegans pqn-62 (16% identical), Drosophila melanogaster Mrtf (15% identical). Paralogues in human: MRTFB (36% identical), MRTFA (33% identical).
Diseases named in the same sentence as MYOCD in open-access papers:
MYOCD is named in the same sentence as 98 diseases in open-access papers, as found by Europe PMC text mining. Sharing a sentence is not in itself a finding about the gene and the disease. The quoted sentences say what the papers report.
cardiac hypertrophy (27 papers, 2012 to 2025). "The exogenous overexpression of ARP5 in murine hearts caused cardiac hypertrophy and fibrosis by suppressing the expression of cardiac muscle genes induced by cardiac MYOCD." (PMID 36610028, 2023). "SCAI is a transcriptional modulator regulating myocardin, implicated in cardiac hypertrophy and hypertension." (PMID 35000590, 2022). "This article focuses on the interaction between MBNL1 and Myocardin and their underlying molecular mechanism in regulating myocardial hypertrophy." (PMID 33295096, 2021). "The expression levels of myocardin is significantly elevated in left ventricular pressure overload-induced murine heart that is associated with cardiac hypertrophy as evidenced by elevated expressions of hypertrophic markers ANP and β-MHC." (PMID 34831061, 2021). "NFATc3 facilitates upregulation of myocardin expression; in contrast, miR-9 acts to reduce myocardin expression, thereby modulating cardiac hypertrophy." (PMID 41226851, 2025). "In vivo studies have shown that KLF4 can modulate isoproterenol-induced cardiac hypertrophy by regulating myocardin (MYOCD) expression and activity, and cardiomyocyte-specific knockdown of KLF4 exacerbates hypertrophy." (PMID 38516000, 2024). "Myocardin was downregulated in the heart of Atp6v0d1AKO mice, and restoring myocardin expression had a therapeutic effect against the development of cardiac hypertrophy and HF in Atp6v0d1AKO mice." (PMID 38505620, 2024). "Excessive expression of ARP5 leads to dysregulation of cardiac MYOCD‐mediated gene expression, resulting in cardiac hypertrophy and fibrosis." (PMID 36610028, 2023). "MBNL1 can up‐regulate the stability of Myocardin mRNA, resulting in the promotion of myocardial hypertrophy and myocardial fibrosis." (PMID 33295096, 2021). "Here, we confirmed that MBNL1 directly binds to Myocardin mRNA to inhibit the degradation of Myocardin mRNA, thereby regulating the occurrence and development of myocardial hypertrophy." (PMID 33295096, 2021). "In this study, we confirmed that MBNL1 can increase the expression of Myocardin by inhibiting the degradation of Myocardin mRNA, which implicate myocardial hypertrophy and its subsequent pathophysiology." (PMID 33295096, 2021). "Previous studies have also confirmed that the forced overexpression of Myocardin in cardiomyocytes can induce myocardial hypertrophy." (PMID 33295096, 2021). "The occurrence and development of myocardial hypertrophy are accompanied by the overexpression of Myocardin in cardiomyocytes." (PMID 33295096, 2021). "Our findings reveal a new function of MBNL1 in cardiac hypertrophy and the molecular network of the post‐transcriptional regulation of Myocardin." (PMID 33295096, 2021). "MBNL1 promoted ISO‐induced cardiac hypertrophy and fibrosis by stabilizing Myocardin mRNA in vivo and in vitro." (PMID 33295096, 2021). "Deacetylation loses the activity of myocardin to regulate the cardiac hypertrophy biomarkers expression." (PMID 33802186, 2021). "Upregulation of Klf4 resulted in myocardin downregulation and development of myocardial hypertrophy." (PMID 33802186, 2021). "Silencing of MYOCD in RAL rats by a cardiac homing peptide conjugated MYOCD siRNA resulted in attenuation of cardiac hypertrophy, fibrosis and restoration of the left ventricular functions." (PMID 30971740, 2019). "Our data document for the first time, the upregulation of cardiac MYOCD in cardio- renal patients and cardiac-specific MYOCD silencing in a cardiorenal model has an integrated beneficiary effect on cardiac hypertrophy, fibrosis and function." (PMID 30971740, 2019). "miR-9, a miRNA of recognized neural functions, reportedly plays a regulatory role in myocardial hypertrophy and is antagonistic to myocardin, a positive mediator of cardiac hypertrophy." (PMID 28866639, 2017).
cardiac hypertrophy (continued). "Studies of miR-9 over-expression or inhibition, under hypertrophic stimulation, demonstrate that this microRNA negatively regulates cardiac hypertrophy, in vivo and in vitro, by targeting Myocardin." (PMID 24113581, 2013). "Myocardin is a direct target of miR-9, so it was studied like a potential regulator of cardiac hypertrophy." (PMID 24113581, 2013). "Another member of NFAT family, NFATc3, is positively regulated by Myocardin, a transcriptional co-activator that promotes cardiac hypertrophy." (PMID 24113581, 2013). "Cardiac hypertrophy, as measured by HW/TL, was also attenuated by increasing myocardin expression." (PMID 38505620, 2024). "KLF-15 expresses in cardiomyocytes and cardiac fibroblasts and upregulates post-natally, inhibiting cardiac hypertrophy by preventing myocardin (MYOCD) and serum response factor (SRF) interactions, thus, diminishing atrial natriuretic factor (ANF) and α-skeletal actin (α-SKA) expression." (PMID 36836777, 2023). "In cardiac hypertrophy, Mhrt can inhibit myocardin expression and attenuate disease progression." (PMID 37197359, 2023). "When cardiac hypertrophy occurred, the overexpression of Myocardin also increased MBNL1 protein levels, which further strengthened the stability of Myocardin mRNA; this in turn maintained the increased abundance of Mycoardin and promoted myocardial remodelling." (PMID 33295096, 2021). "Further, we compared whether siRNA inhibition was more effective at pre- or post-ligation to ascertain the efficacy of MYOCD inhibition on cardiac hypertrophy and fibrosis under these two conditions." (PMID 30971740, 2019). "Also, MYOCD silencing showed beneficial effects by rescuing cardiac hypertrophy, fibrosis, size and function in a cardiorenal rat model." (PMID 30971740, 2019). "Myocardin is a coactivator of serum response factor which specifically expressed in cardiac and smooth muscle cells, and promoter variation of this gene was proposed as a biomarker of cardiac hypertrophy." (PMID 23102236, 2012). "Besides, an interaction between Mhrt and myocardin could suppress cardiac hypertrophy, including the effect of Mhrt on the acetylation of myocardin and myocardin-activating Mhrt transcription." (PMID 37197359, 2023). "Notably, we explored if MYOCD silencing pre- or post-ligation by siRNA could have effective in a RAL rat model showing increased expression of cardiac MYOCD with extensive cardiac hypertrophy and fibrosis." (PMID 30971740, 2019). "It was reported that myocardin was SUMOylated by SUMO1 in K445, and SUMOylation of myocardin by SUMO1 and E3 PIAS1 reversed the expression of myocardial genes and enhanced the cardiac hypertrophy of primary neonatal cardiomyocytes." (PMID 34638970, 2021). "Collectively, these results clearly demonstrate the involvement of acetyltransferase p300 in positive regulator myocardin- and negative regulator IRF9-modulated cardiac hypertrophy in response to ventricular pressure overload." (PMID 34831061, 2021). "CTGF, a key mediator of fibrosis in pathological cardiac hypertrophy, is negatively regulated by KLF15 and increased TGFβ levels activate p38-MAPK signaling which downregulates KLF15 leading myocardin to bind to SRF and to activation of cardiotrophic genes." (PMID 29702551, 2018). "Previous studies have shown that KLF15 inhibits cardiac hypertrophy by repressing the activity of pivotal cardiac transcription factors such as GATA4, MEF2 and myocardin." (PMID 22586493, 2012). "If ASOs or other small molecular inhibitors are designed for the combination of MBNL1/Myocardin and MBNL1/TNF‐α, it may be possible to inhibit cardiac hypertrophy and prevent the apoptosis of cardiomyocytes." (PMID 33295096, 2021). "Phalloidin staining confirmed that MBNL1 could not effectively induce myocardial hypertrophy with Myocardin knockdown." (PMID 33295096, 2021). "Therefore, KLF15 acts as a negative repressor of cardiac hypertrophy via inhibitory competitive binding to myocardin." (PMID 29702551, 2018).
cardiac hypertrophy (continued). "However, it was not until recently that the ability of MYOCD to promote cardiac hypertrophy in vivo was directly examined." (PMID 22666593, 2012). "Although myocardin upregulation completely restored cardiac contractile function in Atp6v0d1AKO mice, the cardiac hypertrophy was ameliorated but not completely corrected, which may be attributed to the effect of PPARγ that was not counteracted by myocardin upregulation." (PMID 38505620, 2024).
atherosclerosis (15 papers, 2014 to 2025). A disease characterized by the build-up of fatty material and calcium deposition in the arterial wall resulting in partial or complete occlusion of the arterial lumen. "For example, MYOCD deficiency exacerbates atherosclerosis by downregulating ABCA1‐dependent cholesterol efflux in VSMCs." (PMID 41031220, 2025). "NF-κB signaling in cultured SMCs interferes with MYOCD function and drives proliferation, and knockout of the gene encoding the required signaling factor IKKβ in SMCs protects against the development of murine atherosclerosis." (PMID 41210961, 2025). "However, miR-145 expression is reduced in human atherosclerotic aortas, associated with decreased SMC contractile markers such as Calponin, α-SMA, and myocardin, implying that loss of miR-145 may exacerbate atherosclerosis." (PMID 38866991, 2024). "Heterozygous deletion of MYOCD, the transcriptional co-activator of most contractile genes, results in accelerated atherosclerosis with more inflammatory cells in mice." (PMID 41210961, 2025). "Compared to myocardin+/+ littermates, myocardin+/− mice on an ApoE−/− background showed increased atherosclerosis with greater concentration of macrophage or macrophage-like cells." (PMID 36035922, 2022). "Despite this, knockout of MYOCD or MRTF-A have directionally opposite effects on atherosclerosis in the mouse." (PMID 34671275, 2021). "It has been previously shown that MRTFA and its related family members MRTFB and myocardin are regulated in vascular injury and atherosclerosis models." (PMID 33597582, 2021). "Additional explanations for the discrepant effects of MRTF-A and MYOCD in atherosclerosis include coactivator-specific effects." (PMID 34671275, 2021). "That is, while homozygous deletion of MRTF-A reduces atherosclerosis, hemizygous deletion of MYOCD increases it." (PMID 34671275, 2021). "Recent research has shown that MYOCD can suppress autophagy by promoting the transcription of miR‐30a, suggesting that MYOCD might influence the regulation of atherosclerosis by modulating autophagic processes." (PMID 41031220, 2025). "Disruption of the SRF–myocardin axis has been mechanistically linked to VSMC phenotypic switching that contributes to fibrous cap thinning, extracellular matrix degradation, and heightened plaque vulnerability in atherosclerosis." (PMID 41246212, 2025). "This is because suppression of myocardin and MRTF activities causes SMC proliferation, especially in atherosclerosis and restenosis, suggesting the importance of SRF/myocardin as a sensor under mechanical stress and growth factor signaling to regulate such phenotypic switches in SMCs." (PMID 32885587, 2021). "In this study, we used cultured cells from non‐defected areas of the aorta in patients with atherosclerosis to indirectly show that miR‐145 modulates the phenotypic switch of VSMCs from a contractile to a proliferative state via KLF5 and MYOCD in atherosclerosis." (PMID 26992033, 2016). "Considering that myocardin is the master regulator of VSMC differentiation, we speculate that myocardin could be differentially regulated during the early and late stages of atherosclerosis." (PMID 25384061, 2014). "LMOD1, another target gene of MYOCD/SRF that falls with increasing age, was uncovered in genome wide association studies for coronary artery disease, raising the possibility LMOD1 depletion may play a role for the age-dependence of atherosclerosis." (PMID 40081573, 2025). "Although much work needs to be done to further establish the detailed mechanisms by which myocardin is differentially regulated, our findings have suggested an important role for TNFα in the regulation of myocardin in VSMCs, and likely the pathogenesis of vascular diseases, such as atherosclerosis." (PMID 25384061, 2014).
atherosclerosis (continued). "TET2, through its role in DNA demethylation, potentially influences the expression of important vascular smooth muscle cell genes such as myocardin (MYOCD) and serum response factor (SRF), which are crucial for smooth muscle function and differentiation in atherosclerosis." (PMID 40428388, 2025). "Modulating the splicing of vital regulators of phenotypic switching, like MYOCD or Bcl-x, could inhibit pathological VSMC dedifferentiation in diseases such as atherosclerosis or restenosis." (PMID 34638554, 2021). "In atherosclerosis, MRTF levels change, and most notable is a fall of MYOCD." (PMID 34671275, 2021). "Relevant to atherosclerosis and CAD, SMAD3 has been shown to directly bind the SMC lineage determining transcription factor myocardin (MYOCD) to regulate transcription of differentiation factors and linked to differentiative and anti-proliferative effects in a number of smooth muscle cell models." (PMID 30307970, 2018). "Therefore, myocardin, as the master regulator of VSMC differentiation, could be involved in the development of atherosclerosis." (PMID 25384061, 2014). "Current research further proposes that miR-145 or miR-143 are part of the regulatory loop for KLF-4, KLF-5, MYOCD, and SRF; critical transcription factors the development of SMC phenotype, and lacking SMC correct differentiation could lead more easily to the development of atherosclerosis." (PMID 36836777, 2023). "Indeed, we found that cultured VSMCs from patients with atherosclerosis had decreased expression of the contractile markers calponin and α‐SMA, along with decreased expression of miR‐145 and MYOCD and increased expression in KLF5 compared with the VSMCs from patients without atherosclerosis." (PMID 26992033, 2016).